TNF (tumor necrosis factor)
Diseases named in the same sentence as TNF in open-access papers (continued):
Sharing a sentence is not in itself a finding about the gene and the disease.
psoriasis (continued). "This study aimed to investigate the frequency of APS-associated autoantibodies in patients with psoriasis receiving different biologics treatments, TNF, IL-17 or IL-23 inhibitors." (PMID 38987260, 2024). "Conversely, psoriasis caused by TNF inhibition displays characteristics more in common with the early phase of classical psoriasis." (PMID 39781163, 2024). "Among the biological agents used for psoriasis, the risk of HBVr with TNF-α inhibitors is well documented." (PMID 39861831, 2024). "It is important to note single nucleotide polymorphisms influence the transcription of TNF and other susceptibility genes related to psoriasis, possibly making PP a factor of genetic susceptibility." (PMID 39823051, 2024). "With regard to inflammatory cytokines, psoriasis is associated with elevated levels of TNFα, IL-23, and IL-17, with these cytokines also having a significant impact on bone erosion in psoriatic arthritis." (PMID 38500951, 2024). "At the same time, identifying factors associated with the success or failure of TNFα inhibitor therapy remains one of the most difficult aspects in psoriasis treatment." (PMID 38999459, 2024). "An experimental study in a mouse model of imiquimod-induced psoriasis concluded that treatment with an inflammasome blocker caused reduced expression of pNF-kB, pSTAT-3, IL-6, and TNFα." (PMID 38965465, 2024). "The systemic inflammation linked to psoriasis, characterized by elevated cytokines such as TNF-α, IL-6, and IL-17, raises the likelihood of metabolic imbalances." (PMID 39767248, 2024). "According to our findings, one of the main mechanisms of Roc in control of Imiq-induced psoriasis can be via its robust anti-inflammatory effect in the suppression of IL-17, IL-23, and TNF-α expression associated with skin inflammation." (PMID 38402151, 2024). "TNF-α has been proven to cause an increase in cell proliferation of human immortalized epidermal cells (HaCaT) in in vitro cell models of psoriasis." (PMID 38611801, 2024). "The pathogenesis of psoriasis is linked to activated T-cells and cytokines such as tumor necrosis factor-α (TNF-α)." (PMID 38275420, 2024). "Patient 3 only showed polymorphisms in a region downstream of CTLA4, which have been previously associated to paradoxical psoriasis to anti-TNF-α." (PMID 38495872, 2024). "The inflammatory processes associated with psoriasis, as well as the altered TNF-adiponectin ratio, accelerate the course of liver disease." (PMID 38473907, 2024). "Psoriasis treatments, particularly systemic therapies like methotrexate, cyclosporin, and TNF inhibitors, carry varying levels of cancer risk, predominantly for non-melanoma skin cancers and lymphoproliferative disorders." (PMID 39766123, 2024). "In psoriasis patients with H. pylori infections, the Psoriasis Area and Severity Index (PASI) scores were higher, so were the mucosal levels of psoriasis-associated cytokines IL-1β, IL-6, IL-8, and TNF-α." (PMID 38347543, 2024). "Genetic polymorphisms in cytokines such as interleukin-1 (IL-1), interleukin-6 (IL-6), and TNF-α have been associated with an increased risk of developing both psoriasis and related systemic diseases, indicating a shared genetic basis for these conditions." (PMID 39189252, 2024). "This study provides the first comprehensive evidence of an increased frequency of APS autoantibodies associated with TNF inhibitor treatment in patients with psoriasis." (PMID 38987260, 2024). "We report a case of PPP/PAO treated with the anti-TNF-α agent adalimumab, which led to the development of PSRs, including psoriasis-like and folliculitis-like rashes, and acute hair loss." (PMID 39469389, 2024). "Classic psoriasis is considered a T-cell-mediated autoimmune disease driven by TNF, while TNFiIP is induced by TNF deficiency." (PMID 39927272, 2024).
psoriasis (continued). "Given the pivotal roles of pro-inflammatory cytokines such as IL-6, TNF-α, IL-1β, and Th17-associated cytokines, in psoriasis development, we compared their expression levels in IMQ-treated WT and CD169-DTR mice." (PMID 38891893, 2024). "Cytokine-targeted nanoparticles: Nanoparticles can be engineered to specifically target and counteract crucial inflammatory cytokines implicated in the development of psoriasis, such as TNF-α and IL-17." (PMID 39188726, 2024). "TNF-α and IL-1 are the driving forces of chronic systemic inflammation predisposing psoriasis patients to CVD and metabolic syndrome." (PMID 38927529, 2024). "The overproliferation of keratinocytes and chronic inflammation in psoriasis are associated with increased concentrations of TNF and vascular endothelial growth factor (VEGF)." (PMID 38398617, 2024). "Short sleep and psoriasis can also be linked through inflammatory networks, particularly tumor necrosis factor-α and IL-6, related to psoriasis pathogenesis and sleep regulation." (PMID 38988999, 2024). "Patients carrying the FBXL19 rs10782001-GG genotype have been shown to be at a higher risk of developing paradoxical psoriasis when treated with anti-TNF drugs." (PMID 38898675, 2024). "The results of this study showed a significant (p < 0.05) association between the PASI score and serum TNF-α levels in psoriasis patients." (PMID 38965465, 2024). "Inflammatory cytokines, mainly TNF-α, IL-17, and IL-23, which occur in the pathogenesis of psoriasis, are thought to increase the risk of CVD, leading not only to psoriasis but also to vascular dysfunction." (PMID 36769825, 2023). "We established and quantified an association of TNF inhibitor monotherapies use by RA patients with psoriasis as an AE." (PMID 37369753, 2023). "When stratifying by disease type, the TNF-α -857 C allele predicted a better response in psoriasis patients (OR = 2.238, 95% CI 1.319–3.790)." (PMID 37372997, 2023). "The hyperproliferation of keratinocytes and chronic inflammation in psoriasis is associated with increased expression of the tumor necrosis factor (TNF) and vascular endothelial growth factor (VEGF)." (PMID 37047297, 2023). "A multicenter study in psoriasis patients with hepatitis B or C reported the occurrence of viral reactivation, showing a higher risk with TNF-α inhibitors than with IL-17 inhibitors." (PMID 38029150, 2023). "Several SNPs in the genes involved in the TNF signaling pathway were implicated in psoriasis susceptibility." (PMID 37569685, 2023). "It has been reported that various cytokine levels such as IL-12, IL-6, IL-17, and TNF-α, which are known to increase in psoriasis, cause an increase in NLR levels." (PMID 37731441, 2023). "In particular, genetic polymorphisms for interleukin (IL)-1, IL-6, and tumor necrosis factor-α have been linked to both psoriasis and periodontal disease, respectively." (PMID 37046012, 2023). "In the univariate Cox proportional hazard regression models, high baseline NLR, psoriasis, and hip involvement were significantly associated with a higher risk of discontinuation of TNF-α blockers." (PMID 36986479, 2023). "The presence of this allele has proved to confer a high risk of suffering from psoriasis, but its association with the response to anti-TNF drugs has yet to be confirmed." (PMID 37240048, 2023). "These SNP variants shed light on the involvement of TNF signaling and NF-κB pathway dysregulation in the pathogenesis of psoriasis." (PMID 37569685, 2023). "The T-allele of TNFRSF1B rs1061622 was associated with the response to anti-TNF-α in the psoriasis subgroup (2 studies, n = 162, OR: 2.62, 95% CI 1.52–4.51)." (PMID 37372997, 2023). "Anti-TNF-α therapy can cause a wide range of dermatological conditions, including local skin irritation or reaction, increased skin infection rates, psoriasis, eczema, anti-TNF-induced cutaneous lupus erythematosus (ATIL), and alopecia areata (AA)." (PMID 37175894, 2023).
psoriasis (continued). "Locally produced tumor necrosis factor-alpha (TNF-α) as well as resident T cells are key players in the chronic inflammation associated with psoriasis." (PMID 38268817, 2023). "According to the United States combined care guidelines, patients with psoriasis treated with TNF is have a lower risk of major adverse cardiovascular events than those treated with methotrexate." (PMID 38149053, 2023). "Wu and Poon reported that the risk of myocardial infarction was substantially reduced in psoriasis patients treated with TNF-α inhibitors compared with untreated patients." (PMID 38149053, 2023). "The activated upstream regulator analysis identified type I IFNs, IFN-γ and TNF as the top mediators promoting psoriasis-associated changes in the SFRP2+ fibroblast subpopulation." (PMID 37308489, 2023). "It is well established that cytokines TNF‐α, IL‐1β, IL‐6, and IL‐17 are involved in tissue inflammation, especially in skin inflammation associated with psoriasis, and can interact with immune cells to exert proinflammatory effects." (PMID 37506136, 2023). "This variant affects the regulation of TNF-alpha-induced signaling pathways, contributing to the dysregulation of the immune responses observed in psoriasis." (PMID 37569685, 2023). "In a cohort of Greek patients with moderate-to-severe psoriasis (n = 228), the rs10484554 polymorphism in the HLA-C gene was associated with a better response to anti-TNF-α, as well as the HLA-A-rs610604 polymorphism with a better response to adalimumab." (PMID 37372997, 2023). "TNF-α inhibitors have been shown to reduce the prevalence of diabetes and metabolic syndrome in patients with psoriasis through clinical studies, but are associated with an increased risk of weight gain, the paradox of which requires further investigation." (PMID 36837593, 2023). "Subsequently, PKA activates the cAMP response element-binding protein (CREB), exerting control over pivotal genes associated with psoriasis, such as IL-2, IL-6, IL-10, and TNFα." (PMID 38258034, 2023). "To date, only the SNP rs553668 in the ADRA2A gene has been associated with anti-TNF treatment response in psoriasis." (PMID 37631238, 2023). "TNF-α antagonist-induced psoriasis, which can emerge de novo or exacerbate a pre-existing form, is the most common dermatological adverse reaction linked to anti-TNF therapy." (PMID 37175894, 2023). "Numerous studies have confirmed TNF-α as one of the key pathogenic cytokines in psoriasis and extensively used for inducing inflammatory conditions in epidermal cell lines." (PMID 37822943, 2023). "Infections, congestive heart failure, demyelinating diseases, drug-induced systemic lupus erythematosus or induction of psoriasis are some of the potential adverse events associated with anti-TNFα therapy." (PMID 36986627, 2023). "The emergence of psoriasis has been identified as an adverse event associated with anti-TNF therapy, with specific instances reported in the literature." (PMID 38137947, 2023). "Psoriasis risk variants have also been evaluated in the spectrum of anti-TNF therapy, with a major example of the HLA-Cw6 allele, an associated susceptibility locus of psoriasis." (PMID 37108251, 2023). "All of the TNF inhibitor monotherapy cohorts exhibited a significant association with psoriasis AEs, supporting the establishment of an association between TNF inhibitor therapeutic use and induced psoriasis." (PMID 37369753, 2023). "The risk of COVID-19 infection in psoriasis patients receiving TNF-α, IL-17, IL-12, and IL-23 inhibitors was also investigated in different cohort studies, systematic evaluations, and meta-analyses." (PMID 38029150, 2023). "We also discovered that all of the non-TNF inhibitor cohorts, except tofacitinib, were statistically significantly associated with psoriasis, though to a lesser extent than certolizumab pegol." (PMID 37369753, 2023).
psoriasis (continued). "Psoriasis is caused primarily by pro-inflammatory cytokines such as interleukin 6 (IL-6), interleukin 1β (IL-1β), and tumor necrosis factor-alpha (TNF-α) from stressed keratin-forming cells." (PMID 37643205, 2023). "Our study revealed a statistically significant association between the response to anti-TNF and IL-12/23 in psoriasis and glial cell proliferation." (PMID 37631238, 2023). "Candidate-gene approaches have governed the pharmacogenetic studies conducted in the TNFi therapy in patients with psoriasis in search of polymorphisms mapped in TNF and susceptibility-related genes." (PMID 37108251, 2023). "It has been shown that after treatment with TNF-α inhibitor in patients with psoriasis, serum levels of Th1-associated T-bet and related cytokines IFN-γ, IL-6 and TNF-α were significantly decreased when compared to the baseline period." (PMID 37270497, 2023). "The RORs and 95% CIs of the non-TNF inhibitor cohorts demonstrate the statistically significant risk of developing psoriasis for RA patients using any of the studied monotherapy cohorts, except tofacitinib." (PMID 37369753, 2023). "The RORs and their 95% CIs demonstrate the risk of induced psoriasis in RA patients using TNF inhibitor monotherapies." (PMID 37369753, 2023). "Low adiponectin levels in patients with psoriasis are associated with increased TNF-α and IL-6 levels and are inversely correlated with PASI scores." (PMID 38003284, 2023). "We discovered that all TNF inhibitor treatments have a statistically significant association with psoriasis in RA patients." (PMID 37369753, 2023). "We have previously found an association between low levels of IL-6 and TNF-α at baseline and a response to brodalumab in patients with psoriasis." (PMID 37047086, 2023). "The levels of amino acids were also associated with the severity of psoriasis and the effects of anti-TNFα treatment." (PMID 37205116, 2023). "In the pathogenesis of psoriasis, inflammatory cytokines such as TNF-α, IL-23, and IL-17 form the primary pathogenesis and cause systemic inflammation." (PMID 36769825, 2023). "The exact cause of psoriasis is not fully understood, though it has been reported that proinflammatory cytokines such as IL-17A, TNF-α, and IFN-γ play an important role in the pathogenesis of psoriasis." (PMID 37686332, 2023). "In fact, the study revealed more frequent occurrence of the TNF-α rs1799964 allele, and less frequent occurrence of the HLAcW6 allele among the patients presenting paradoxical psoriasis." (PMID 38098849, 2023). "Psoriasis is an immune-mediated, inflammatory disease, and it is well known that the tumor necrosis factor (TNF)-α inhibitors are associated with enhanced risk of reactivation of latent tuberculosis infection." (PMID 37514118, 2023). "In this study, we analyzed over 880 thousand RA reports from FDA Adverse Event Reporting System (FAERS) and quantifed the evidence using the latest population scale dataset for a statistically significant association of psoriasis with TNF inhibitor use." (PMID 37369753, 2023). "Pathologically, psoriasis is associated with an increase in the production of pro-inflammatory cytokines, such as tumor necrosis factor-alpha (TNF-α), interleukins (IL-1 and IL-17), and interferon-γ (IFN-γ), that drive the development of the disease." (PMID 37047363, 2023). "Tumor necrosis factor, locating near the focus point, therapy sometimes cause paradoxical enhanced reactions in psoriasis." (PMID 38304250, 2023). "Data regarding the effect of TNF-α inhibitors on the cardiovascular risk of patients with psoriasis are insufficient, according to a relevant systematic review." (PMID 37629526, 2023). "The suppression of psoriasis-related, proinflammatory, and Th17-associated cytokines, such as tumor necrosis factor (TNF)-α, IL-17A, and IL-23, was observed in mice fed with Lactobacillus pentosus." (PMID 36902001, 2023).
psoriasis (continued). "The relevant role of TNF-α inhibitors in modulating the CV risk in psoriasis was also demonstrated by their ability to reverse the microvascular dysfunction measured by CFR." (PMID 35686132, 2022). "Tumor necrosis factor-α, dendritic cells, interleukin-1, -6, and -8, and T-cells all contribute substantially to the pathogenesis of psoriasis and increase the risk of other systemic diseases." (PMID 35163689, 2022). "Several studies have shown that pro-inflammatory cytokines in psoriasis, such as IL-6, IL-17, and TNF-α, are associated with psychiatric disorders." (PMID 35805960, 2022). "This study aimed to identify genetic biomarkers of anti-TNF-α response in Chinese psoriasis patients using a genome-wide association approach." (PMID 36059983, 2022). "The activation of NF-κB pathways is the hallmark of psoriasis, and results in the production of excessive inflammatory cytokines (e.g., TNF-α, IL-6, IL-17), which leads to the progression of psoriasis." (PMID 35335900, 2022). "Auto-inflammation driven by T cells, TNF-α, IL-23, and IL-17 underlies the pathogenic pathway of psoriasis." (PMID 35566548, 2022). "TNFα is also directly implicated in psoriasis pathogenesis and TNFα inhibitors are recommended as a monotherapy treatment option for adults with moderate-to-severe psoriasis." (PMID 34816303, 2022). "IL-17A is also intimately implicated in the development of TNF-driven autoimmune disorders such as psoriasis, spondyloarthritis and Crohn’s disease." (PMID 36396641, 2022). "Three miRNAs (miR- 203, miR-146a and miR-125b) currently associated with psoriasis are involved in the natural immune response and the TNF-α pathway." (PMID 35356223, 2022). "UST is another safe and effective option in the treatment of IBD associated with psoriasis and, also, in the management of anti-TNF paradoxical psoriasis." (PMID 35160280, 2022). "Increased M1 polarization was associated with higher disease severity in psoriasis, returning to baseline after successful treatment by TNF-α inhibitors." (PMID 35837394, 2022). "It has become clear that the tumor necrosis factor-/Interleukin-23/Interleukin-17A pathway is the primary method causing the increased inflammation and damage in psoriasis." (PMID 36106203, 2022). "The aberrant immune and epidermal response seen in psoriasis is maintained by pathogenic crosstalk between epithelial and immune cells, and it is primarily driven by proinflammatory molecules, such as TNF-α, IL-23 and IL-17." (PMID 35008970, 2022). "Anti-TNFα agents were associated with decreased risk for comorbid AD in patients diagnosed with psoriasis." (PMID 36226313, 2022). "Visceral fat was associated with psoriasis, hyper-triglyceridemia, low high-density lipoprotein, and type 2 diabetes, and these associations were linked to serum IL-6, adiponectin, tumor necrosis factor, and insulin resistance." (PMID 35757712, 2022). "Cells within a single CD8 TEM cluster enriched among PSO subjects (cluster 11) showed a strong upregulation of CCL4, a CD8+ T cell recruiting chemokine associated with psoriasis, along with other inflammatory cytokines and chemokines (TNF, IFNG, CCL3, CCL4L2)." (PMID 35309349, 2022). "In children, however, it is reported in the literature that the lesional tissue of patients with pediatric psoriasis is associated with higher levels of TNF-α, IL-22-producing T cells and relatively fewer IL-17-producing T cells compared with adult psoriasis." (PMID 36232430, 2022). "Paradoxical reactions, such as palmoplantar psoriasis and inverse psoriasis, have been described in the literature in association with anti-TNF-α inhibitors, secukinumab, and ustekinumab." (PMID 35843765, 2022). "According to some, patients with psoriasis have multiple risk factors for serious infections, such as immune dysregulation characterized by an increase of TNF and IL-17, and the use of systemic immunosuppressants." (PMID 35203438, 2022).